APOE (apolipoprotein E)
Diseases named in the same sentence as APOE in open-access papers (continued):
Sharing a sentence is not in itself a finding about the gene and the disease.
atherosclerosis (continued). "RAP@T/R NPs significantly blocked the development of atherosclerosis and suppressed the systemic and local inflammation in ApoE-/- mice." (PMID 35673565, 2022). "Especially in the setting of diabetes, the protective role of TRAIL against diabetes-related atherosclerosis was demonstrated more than a decade ago in apolipoprotein E knockout mice ApoE (−/−) which were used as an experimental model of atherosclerosis." (PMID 35328646, 2022). "Idebenone, which is a compound similar to co-enzyme Q10, also increases SIRT3 activity and further activates SOD2, which suppresses ROS to ameliorate atherosclerosis in ApoE−/− mice." (PMID 35453391, 2022). "ApoE−/− mice show impaired plasma lipoproteins clearance and they develop atherosclerosis in a short time." (PMID 35571092, 2022). "In conclusion, we report the pharmacological effects of HU in the treatment of atherosclerosis in ApoE-/- mice." (PMID 36451858, 2022). "In addition, to validate whether NET-mediated suppression of macrophage autophagy plays an important role for developing atherosclerosis in vivo, loss-of-function animal models such as macrophage-specific Atg5 knockout mice should be crossed with ApoE−/−; Neu-Pad4−/−mice." (PMID 35923856, 2022). "The ARCR herb pair regulated blood lipid metabolism and attenuated atherosclerosis in ApoE-/- mice by regulating the M1/M2 and Th1/Th2 immune balance and activating the STAT6 signaling pathway." (PMID 35178108, 2022). "In this study, we generated SLE mice prone to atherosclerosis (ApoE−/− Fas−/−) and provided direct evidence demonstrating a pathogenic role MDSCs in vivo." (PMID 35850768, 2022). "The effects and mechanisms of action of DSHT were studied in well-established atherosclerosis-prone ApoE-/- mice." (PMID 35207485, 2022). "Aguilar and colleagues (2014) provided butyrate supplementation to several models of atherosclerosis: a human endothelial cell line and an ApoE knockout mouse model." (PMID 35056557, 2022). "The results thus far show that the A2Kb-Tg ApoE–/– mouse is a valid experimental model for atherosclerosis." (PMID 35536648, 2022). "The focus of this study was to develop an atherosclerosis model with hypertension, and there have been few comparisons between ApoE/NOS3−/− and NOS3−/− mice." (PMID 36360235, 2022). "Apolipoprotein E has been proven to affect atherosclerosis, neurodegeneration, and the process of nerve damage repair." (PMID 35154509, 2022). "On the contrary, DCs pulsed with malondialdehyde modified LDL (MDA-LDL-DCs) and injected in ApoE–/– mice increased atherosclerosis." (PMID 35966516, 2022). "The most common phenotypes of ApoE-KO mice are hyperlipidemia and the spontaneous development of atherosclerosis." (PMID 36360235, 2022). "By comparison, C57BL6/J animals, which lack significant atherosclerosis compared to ApoE−/− animals, share only 17% of IgM and 16% of IgG1 targets." (PMID 36461105, 2022). "We previously demonstrated that P. gingivalis, T. denticola, T. forsythia, and F. nucleatum induced atherosclerotic aortic plaque in an ApoE−/− model of atherosclerosis." (PMID 35563501, 2022). "We aimed to investigate the effect of anakinra, a recombinant human IL-1 receptor antagonist, on the progression of atherosclerosis in apolipoprotein E knockout (ApoE–/–) mice." (PMID 35563294, 2022). "The aim of this study is to explore the anti-atherosclerosis effect of GPE on the inflammation and intestinal microbiota in a high-fat diet and atherosclerosis induced by choline in ApoE−/− mice." (PMID 36145277, 2022). "A study using atherosclerosis‐prone apolipoprotein E (apoE)‐knockout mice indicated that a high‐cholesterol diet significantly induced the progression and vulnerability of atherosclerotic plaques." (PMID 35569818, 2022).
atherosclerosis (continued). "In conclusion, our report has shown the metabolic regulation effects of SAP efficiency on atherosclerosis in ApoE−/− mice." (PMID 36557316, 2022). "Our aim was to analyze the association of APOE e4 with carotid atherosclerosis and the association of CRF with atherosclerosis in APOE e4 carriers." (PMID 36357490, 2022). "ApoE−/− is considered to be a good model for the study of atherosclerosis, the pathological process of which is similar to that of humans." (PMID 36557316, 2022). "Next, we examined apoE KO rabbits, which have higher TC and TG levels than WT rabbits, and more atherosclerosis in the aorta and coronary arteries." (PMID 35712258, 2022). "Based on these encouraging data, the targetability and anti-AS effects will be further investigated in depth in an apolipoprotein E-knockout (apoE−/−) mouse model of atherosclerosis." (PMID 35745836, 2022). "We show that SMC-specific ablation of NEMO (NEMOSMCiKO) inhibited high fat diet induced atherosclerosis in ApoE−/− mice." (PMID 35869246, 2022). "Glass and Witztum listed several such cytokines and cytokine receptors, whose knockout almost completely inhibits atherosclerosis in apoE−/− mice." (PMID 35464770, 2022). "The ApoE−/− mouse as an established atherosclerosis model was first used to identify possible lipid markers for the subsequent evaluation of human atherosclerotic vessel samples." (PMID 34797426, 2022). "In high-fat diet ApoE knockout mice, administration of SS-31 inhibits cholesterol uptake, which in turn inhibits foam cell formation and atherosclerosis progression." (PMID 36559254, 2022). "We therefore aimed to generate a population of PD-L1hi B cells ex vivo, to adoptively transfer in WTD fed apoE−/− mice to halt atherosclerosis." (PMID 35187121, 2022). "ApoE−/− mice develop spontaneously atherosclerosis, highlighting the significance of this apolipoprotein in atheroprotection." (PMID 36297390, 2022). "A lineage-tracing system, induced by myh11 promoter, is developed in the apoE–/– mouse model of atherosclerosis." (PMID 35498045, 2022). "But interestingly, previous studies have also found that overexpression of eNOS can accelerate the development of atherosclerosis in ApoE-KO mice." (PMID 35047104, 2022). "A widely used pharmacology drug solubilizer and penetration enhancer, NMP (N -methyl-2-pyrrolidone), also has anti-inflammatory properties, confirmed in ApoE−/− mouse model of atherosclerosis." (PMID 35203463, 2022). "For these reasons, 18 miRNAs were selected by searching in PubMed and GEO database for their possible role in promoting atherosclerosis and analyzed by RT-qPCR in the aorta from ApoE−/− and wild-type mice." (PMID 36142173, 2022). "At baseline (0 weeks WD), very low levels of RIPK1, RIPK3, and MLKL were observed in the atherosclerosis-prone aortic arch of both ApoE−/− and ApoE−/− Fbn1C1039G+/− mice but the expression levels increased during plaque progression." (PMID 35625752, 2022). "It is well known that atherosclerosis is an advanced disease, and so we performed a regression model by treating ApoE-/- mice that were fed WD alone for 10 weeks with bufalin for 13 weeks during WD feeding." (PMID 36263184, 2022). "This study aimed to investigate the anti-atherosclerosis effects of chronic (16 weeks) treatment with anakinra to block IL-1 activity in apolipoprotein E knockout (ApoE–/–) mice fed an atherogenic diet, and to explore its possible mechanisms of action." (PMID 35563294, 2022). "IFNγ activates macrophages, increasing their inflammatory potential, and during atherosclerosis has a potent proatherogenic effect on plaque formation with deletion of Tbet and IFNγ alleviating this plaque formation in ApoE−/− mice." (PMID 36461105, 2022).
atherosclerosis (continued). "Altogether, our findings indicated that ox‐LDL‐M‐EVs carrying miR‐19b‐3p can facilitate the progression of atherosclerosis in ApoE−/− mice." (PMID 34910364, 2022). "These inhibitors reduce the development of atherosclerosis in APOE*3-Leiden and low-density lipoprotein receptor−/− mice." (PMID 36313564, 2022). "Overexpression of HO-1 via adenovirus-mediated gene transfer in vascular cells attenuates the development of atherosclerosis in ApoE-/- mice." (PMID 35281895, 2022). "In this study, bufalin treatment of ApoE-/- mice ameliorated atherosclerotic plaque formation in an ApoE-/- prevention model and regression model, suggesting that bufalin plays an important protective role against atherosclerosis." (PMID 36263184, 2022). "In vivo administration of ADMA worsened aortic inflammation, impaired cholesterol metabolism and promoted atherosclerosis in apoE−/− mice." (PMID 35160173, 2022). "We therefore crossed C57BL/6J p16-3MR with C57BL/6J ApoE−/− mice and studied atherosclerosis after chronic ablation of p16-expressing cells." (PMID 34142149, 2022). "ApoE and its three isoforms, ApoE2, ApoE3, and ApoE4, play significant roles in plasma cholesterol metabolism, atherosclerosis, and hypercholesterolemia." (PMID 36430365, 2022). "Here, we show that 12 weeks of regular exercise training on a treadmill significantly decreased lipid accumulation and foam cell formation in ApoE−/− mice fed with a Western diet, which plays a critical role in the process of atherosclerosis." (PMID 35409148, 2022). "In our published paper, we demonstrated that ApoE−/− mice with a high-fat diet accelerated the formation of atherosclerosis and depression-like behavior changes." (PMID 35558553, 2022). "The potential therapeutic role of hidrosmin in atherosclerosis was explored in STZ-induced diabetic ApoE KO mice." (PMID 36552707, 2022). "Affibody molecule neutralizing IL17A, or sham were administered in vitro to human aortic smooth muscle cells (HAoSMCs) and murine NIH/3T3 fibroblasts and in vivo to atherosclerosis-prone, hyperlipidaemic ApoE−/− mice." (PMID 35282365, 2022). "Despite the accelerated atherosclerosis development, a major limitation of the ApoE−/− mouse model is that the lesions rarely rupture and hence do not lead to thrombosis, whereas vascular occlusion is common in humans." (PMID 34797426, 2022). "Treatment with Rac1 inhibitor elevates endothelial function and reduces atherosclerosis in ApoE knockout mice." (PMID 36185329, 2022). "In one study, ApoE knockout rats showed early signs of lipid deposition and atherosclerosis after psychological stress induced by occlusal disharmony." (PMID 36361754, 2022). "Investigating atherosclerosis and endothelial dysfunction has mainly become established in genetically modified ApoE−/− or LDL-R−/− mice transgenic models." (PMID 35648220, 2022). "In these lines, RIPK3 activation and subsequent necroptosis in atheroma macrophages lead to local and systemic inflammatory responses associated with atherosclerosis in low-density lipoprotein (LDL) receptor- and apolipoprotein E (APOE)-deficient mice." (PMID 36361505, 2022). "Next, we examined the occurrence of a similar KDM subtype expression pattern in the aorta of ApoE-/- mice fed a high-fat, cholesterol-rich diet (HD) for 14 weeks, an experimental set-up partially resembling human atherosclerosis." (PMID 36552592, 2022).
atherosclerosis (continued). "In the potassium oxonate-treated ApoE−/−−/− mice, atherosclerosis was accelerated along with elevated serum cholesterol levels in the hyperuricemic state, which can be ameliorated by dioscin." (PMID 35565954, 2022). "A previous study has shown that the elevated NK cells via adoptive transfer doubled atherosclerotic lesion size in ApoE-/-Rag2-/-IL2rg-/- mice, indicating that SnPP can exacerbate atherosclerosis through NK cells." (PMID 35281895, 2022). "Previous studies have shown that CIH can induce dyslipidemia and atherosclerosis in ApoE−/− mice by inhibiting the expression and activity of LPL and affecting the expression of Angptl4, a potential inhibitor of LPL in adipose tissue but not in heart tissue." (PMID 36285165, 2022). "Intriguingly, in ApoE-KO mice with Hmox1 deletion, the atherosclerosis and oxidative stress were accelerated." (PMID 35204118, 2022). "ApoE−/− mice are a validated model for human atherosclerosis, and bacterial intranasal inoculation is a well validated model for human respiratory infections." (PMID 35778475, 2022). "Previous studies on the function of the ApoE gene have focused on its implication in atherosclerosis and hyperlipidemia." (PMID 36139057, 2022). "One explanation of this is the fact that based on the mouse model (ApoE–/–), IL-1α is primarily responsible for atherosclerosis." (PMID 36082127, 2022). "Our group found that deletion of the SAP gene can significantly inhibit the formation of atherosclerosis and the aggregation of foam cells in ApoE−/− mice." (PMID 36557316, 2022). "ECs in ApoE−/− mice and human atherosclerotic plaques exhibit mitochondrial DNA (mtDNA) damage due to ROS, which correlated with the extent of atherosclerosis." (PMID 35348183, 2022). "One study from Tang laboratory have revealed that periaortic knockdown of ribosomal protein S3A (RPS3A) in mouse PVAT impaired PVAT browning, promoted vascular inflammation and atherosclerosis development by modulating UCP-1 expression in ApoE-/- mice." (PMID 36172381, 2022). "Subsequently, ApoE−/− mice were used to construct atherosclerosis model, and the efficacy of QHZYF was evaluated by oil red O staining, HE staining, Masson staining, Sirius red staining, and serum lipid detection." (PMID 36518993, 2022). "The data suggested that the ARCR herb pair attenuated atherosclerosis in ApoE-/- mice by regulating M1/M2 and Th1/Th2 immune balance via activation of the STAT6 signaling pathway." (PMID 35178108, 2022). "At present, studies have confirmed that ApoE is related to atherosclerosis (AS), Alzheimer’s disease (AD) and other vascular diseases and CNS dysfunction." (PMID 36188475, 2022). "In summary, in addition to its role in modulating plasma lipid homeostasis, apoE also impacts atherosclerosis development and progression via modulating cell functions in a cell type-specific and isoform-dependent manner." (PMID 36077289, 2022). "In atherosclerosis, MitoTEMPOL improves the vulnerability characteristics of atherosclerotic plaques in ApoE-/-/SOD2+/- mice by reducing the expression of calpain-2, caspase-3 and matrix metalloproteinase-2, smooth muscle cell apoptosis and matrix degradation." (PMID 36559254, 2022). "Splenectomy was shown to exacerbate atherosclerosis in ApoE−/− mice, accompanied by a decrease in anti-ox-LDL antibody levels." (PMID 36204316, 2022).
atherosclerosis (continued). "Here, we demonstrated that supplementation with allicin or raw garlic juice inhibited TMAO production through carnitine metabolism by the gut microbiota in both mice and humans and prevented carnitine-induced atherosclerosis in ApoE−/− mice." (PMID 35087050, 2022). "To further examine the role of VSMC CRP4 in the pathogenesis of atherosclerosis, we examined the overall plaque burden and plaque size in ApoE−/−/CRP4+/+ and dKO mice." (PMID 35456043, 2022). "PON2/ApoE−/− double knockout mice show increased atherosclerosis with elevated mitochondrial oxidative stress." (PMID 36497101, 2022). "In this study, we aimed to demonstrate that oral administration of HU is effective in the treatment of atherosclerosis in ApoE knockout (ApoE-/-) mice." (PMID 36451858, 2022). "Inhibition of TLR/NF-κB signalling specifically in vascular endothelial cells protected ApoE−/− mice from atherosclerosis by preventing the expression of proinflammatory factors and the recruitment of monocytes to the developing plaques." (PMID 35869246, 2022). "Previous studies have shown that a vaccine derived from ApoB-100 exerts a therapeutic effect by inhibiting atherosclerosis, and a P210 vaccine can reduce the progression of atherosclerosis in ApoE−/− mice by approximately 40%." (PMID 35391927, 2022). "TRAF-STOP therapy with either SMI 6860766 or 6877002 decreased the onset of early atherosclerosis and stopped the progression of established atherosclerosis in ApoE−/− mice." (PMID 36703734, 2022). "In the ApoE−/− mouse model, all possible forms of atherosclerosis can be observed and even accelerated by special diets." (PMID 35760040, 2022). "The apoE mimetic peptide EpK enhances cholesterol efflux from cells and has beneficial effects in animal model of atherosclerosis." (PMID 36035124, 2022). "In this study, we evaluated the effect of homoplantaginin and its derivative dihydrohomoplantagin on oxLDL-induced endothelial cell injury and atherosclerosis in apoE-/- mice." (PMID 35335352, 2022). "Instead, we prefer ApoE−/− Fbn1C1039G+/− mice for pharmacological studies because signs of necroptosis mainly occur in the more advanced stages of atherosclerosis." (PMID 35625752, 2022). "Desulfovibrio, Ruminococcaceae, Tyzzerella, and Lachnospiraceae, associated with obesity-induced inflammation, dyslipidemia, and atherosclerosis, were significantly elevated in the ApoE WD group." (PMID 35256637, 2022). "A lower expression of Sirtuin 1 (SIRT1) leads to ovariectomy (OVX)-induced arterial senescence and atherosclerosis in apolipoprotein E-knockout (ApoE-KO) mice." (PMID 35280995, 2022). "Both direct thrombin and factor Xa inhibition reduced the development of atherosclerosis in ApoE-/- mice." (PMID 36422558, 2022). "Adoptive transfer of splenic B cells from atherosclerosis-prone ApoE−/− animals into young ApoE−/− recipients was also shown to prevent atherosclerosis." (PMID 36204316, 2022). "The expression of RIPK1 is also increased in early-stage atherosclerotic lesions of both human atherosclerosis patients and ApoE−/− mice." (PMID 39872161, 2022). "The atherosclerosis-prone ApoE−/− mouse is one of the most widely used murine models for the study of atherosclerosis." (PMID 34797426, 2022). "The biological functions of the APOE subtypes determine the metabolism of blood plasma lipids and the progression of atherosclerosis." (PMID 36426228, 2022). "Ruminococcaceae family was positively correlated with atherosclerosis lesion size in apoE-/- mice, and was also positively correlated to blood IgM levels and colitis." (PMID 35334879, 2022).